PDE1A (phosphodiesterase 1A)
Description:
Calcium/calmodulin-dependent cyclic nucleotide phosphodiesterase with a dual specificity for the second messengers cGMP and cAMP, which are key regulators of many important physiological processes. Has a higher efficiency with cGMP compared to cAMP.
Synonyms: Cam-PDE 1A; CAM-PDE-1A; HCAM-1; HCAM1; HSPDE1A
Tractability: Small molecule: an approved drug acts on it; a high-quality ligand is known; it belongs to a druggable protein family. PROTAC: ubiquitination databases record sites on it; its protein half-life has been measured; a small molecule that binds it is known.
Target class: Phosphodiesterase; Phosphodiesterase 1A; Enzyme; Phosphodiesterase 1
Chemical probes: ITI-214 (high quality)
Gene: Protein-coding gene on chromosome 2 (182,139,968 to 182,523,359, reverse strand). Ensembl gene ENSG00000115252.
Subcellular location (Human Protein Atlas): Nucleoplasm
Pathways (Reactome):
Signal Transduction: Cam-PDE 1 activation; G alpha (s) signalling events
Hemostasis: cGMP effects
Gene Ontology:
Molecular function: 3',5'-cyclic-AMP phosphodiesterase activity; 3',5'-cyclic-GMP phosphodiesterase activity; 3',5'-cyclic-nucleotide phosphodiesterase activity; calmodulin-activated dual specificity 3',5'-cyclic-GMP, 3',5'-cyclic-AMP phosphodiesterase activity; calmodulin-activated 3',5'-cyclic-GMP phosphodiesterase activity; phosphoric diester hydrolase activity
Biological process: negative regulation of cAMP/PKA signal transduction; cGMP catabolic process; regulation of smooth muscle cell apoptotic process; regulation of smooth muscle cell proliferation; signal transduction
Cellular component: cytosol; neuronal cell body
Genetic constraint (gnomAD): Loss-of-function variants: 17 observed, 29.84 expected, observed/expected ratio (o/e) 0.57, 90% interval 0.39 to 0.85. The upper end of that interval is the gene's LOEUF score, 0.85, which puts it in group 3 of 6, group 1 being the genes least tolerant of losing a copy. Missense variants: 363 observed, 393 expected, observed/expected ratio (o/e) 0.92, 90% interval 0.85 to 1.01. Synonymous variants: 149 observed, 135.97 expected, observed/expected ratio (o/e) 1.1, 90% interval 0.96 to 1.25.
Homologues: Orthologues: chimpanzee PDE1A (97% identical), guinea pig PDE1A (95% identical), macaque PDE1A (95% identical), rat Pde1a (91% identical), mouse Pde1a (91% identical), dog PDE1A (90% identical), pig PDE1A (90% identical), rabbit PDE1A (90% identical), tropical clawed frog pde1a (75% identical), zebrafish pde1a (73% identical), Caenorhabditis elegans pde-1 (45% identical). Paralogues in human: PDE1C (67% identical), PDE1B (57% identical), PDE3A (29% identical), PDE3B (29% identical), PDE4D (28% identical), PDE4C (28% identical), PDE4A (27% identical), PDE4B (27% identical), PDE8A (24% identical), PDE6C (24% identical), PDE11A (24% identical), PDE8B (24% identical), and 8 more.
Diseases named in the same sentence as PDE1A in open-access papers:
PDE1A is named in the same sentence as 49 diseases in open-access papers, as found by Europe PMC text mining. Sharing a sentence is not in itself a finding about the gene and the disease. The quoted sentences say what the papers report.
cardiac hypertrophy (5 papers, 2010 to 2024). "An increase in PDE1 activity and PDE1A expression has been reported to be associated with cardiac hypertrophy induced by abdominal aortic banding in Sprague-Dawley rats, and more recently by neurohumoral stimuli such as angiotensin II and isoproterenol." (PMID 21151982, 2010). "Although PDE1A plays a crucial role in cardiac hypertrophy by regulating cGMP degradation, evidence suggests that PDE1C is also involved in regulating cardiomyocyte hypertrophy by regulating cAMP degradation." (PMID 37971403, 2024). "PDE1A has also been shown to play an important role in cardiac hypertrophy and fibrosis in cardiac fibroblasts." (PMID 34944010, 2021). "A study shows that mRNAs of PDE1A and PDE1C are also present in the human heart and that PDE1A plays a critical role in PKG-dependent cardiac hypertrophy, while the use of a PDE1 inhibitor would decrease protein synthesis." (PMID 31640161, 2019). "Consistently, PDE1A suppression of cardiac hypertrophy also occurs in a PKG-dependent manner." (PMID 29690591, 2018). "Thus, to our knowledge, it is the first time that, additively to PDE1A, PDE1C is shown to be associated with cardiac hypertrophy in the heart." (PMID 21151982, 2010). "Further investigation into the differential mechanisms of PDE1A and PDE1C in cardiac hypertrophy and HF will aid in developing PDE1 isozyme-selective inhibitors to achieve specific pharmacological effects." (PMID 37971403, 2024).
cystic kidney disease (3 papers, 2017 to 2020). A congenital or acquired kidney disorder characterized by the presence of renal cysts. "In the current study, we detected the rs182089527 mutation in PDE1A in 5 patients suffering from cystic kidney disease." (PMID 29262781, 2017). "Pde1a mutant mice had a mild renal cystic disease and a urine concentrating defect on a wild-type genetic background and aggravated renal cystic disease on a Pkd2WS25/– background." (PMID 33013477, 2020). "At these ages small renal cysts were observed in 9 of 19 (47%, 8 Pde1aDel15/Del15 and 11 Pde1aInsA/InsA mice) and 17 of 27 (63%, 20 Pde1aDel15/Del15 and 7 Pde1aInsA/InsA mice) Pde1a mutant compared to 1 of 12 (13%, P = 0.046) and 1 of 10 (10%, P = 0.008) wild-type mice, respectively." (PMID 28750036, 2017). "Pde1a mutants had a mild renal cystic disease and a urine concentrating defect (associated with upregulation of PDE4 activity and decreased protein kinase A dependent phosphorylation of aquaporin-2) on a wild-type genetic background and aggravated renal cystic disease on a Pkd2WS25/- background." (PMID 28750036, 2017).
Hypertension (3 papers, 2017 to 2020). The presence of chronic increased pressure in the systemic arterial system. "PDE1 attracted interest in the context of arterial hypertension when an association of PDE1A single nucleotide polymorphism with diastolic and mean blood pressure was described in human genetics study." (PMID 33013477, 2020).
metastatic disease (3 papers, 2021 to 2025). "Mechanistic data uncover a novel PDE1A/YTHDF2/STAT3 axis driving NSCLC metastasis and suggest potential therapeutic strategies for metastatic disease." (PMID 40704992, 2025).
pulmonary arterial hypertension (3 papers, 2019 to 2022). Pulmonary arterial hypertension (PAH) is a group of diseases characterized by mean pulmonary artery pressure >20 mmHg and elevated pulmonary arterial resistance leading to right heart failure. "Some animal studies have shown that the inhibition of PDE1A treats pulmonary arterial hypertension by reversing pulmonary vascular remodeling and right heart hypertrophy." (PMID 36531729, 2022). "PDE1A had also been identified as responsible for pulmonary hypertension in pulmonary arterioles." (PMID 35822023, 2021).
acute lymphoblastic leukemia (2 papers, 2021 to 2025). Leukemia with an acute onset, characterized by the presence of lymphoblasts in the bone marrow and the peripheral blood. "Specifically, thymoquinone suppresses PDE1A expression and inhibits UHRF1 via a p73-dependent mechanism, suggesting potential application in acute lymphoblastic leukemia (ALL) therapy." (PMID 41179677, 2025).
asthma (2 papers, 2021 to 2025). "Additionally, genes involved in neurotransmitter signaling, such as SYN3 and PDE1A, indicate a potential neuro-immune connection in asthma and eczema." (PMID 41561239, 2025). "Thus, Vinp, a PDE1 inhibitor, can affect asthma through PDE1A, 1B, and 1C inhibition." (PMID 33914833, 2021).
idiopathic pulmonary fibrosis (2 papers, 2021 to 2026). Idiopathic pulmonary fibrosis (IPF) is a nonneoplastic pulmonary disease that is characterized by the formation of scar tissue within the lungs in the absence of any known cause. "Previous studies have reported miR-541-5p as a key effector in lung fibroblasts, which influences bleomycin-induced pulmonary fibrosis by regulating the target gene PDE1A (phosphodiesterase 1A)." (PMID 34768749, 2021).
Kidney Cyst (2 papers, 2015 to 2017). Abnormal fluid filled sac within the kidney, either acquired or congenital. "Our study provides genetic evidence that the rs182089527 mutation in PDE1A is involved in the development of NL and kidney cysts, which should help to improve personalized medicine for diagnosis and treatment." (PMID 29262781, 2017). "Taken all together, we propose that as in kidney cysts, in KV cells the drop of the intracellular Ca2+ levels caused by the knockdown of Polycystin-2, leads to the activation of AC5 and AC6 and to the inhibition of PDE1A, raising the levels of cAMP and, thus, activating CFTR." (PMID 26432887, 2015).
non-small cell lung carcinoma (2 papers, 2025). A group of at least three distinct histological types of lung cancer, including non-small cell squamous cell carcinoma, adenocarcinoma, and large cell carcinoma. "Phosphodiesterase 1A (PDE1A) knockdown suppresses the metastasis of non-small cell lung cancer (NSCLC) cells." (PMID 40704992, 2025). "Phosphodiesterase 1A (PDE1A) promotes the metastasis of non-small cell lung cancer (NSCLC) cells via the STAT3 signaling pathway." (PMID 40704992, 2025).
Alzheimer disease (1 paper, 2022). A progressive, neurodegenerative disease characterized by loss of function and death of nerve cells in several areas of the brain leading to loss of cognitive function such as memory and language. "Phosphodiesterase 1A (PDE1A) localizes to the nucleus and large membrane fractions in both conditions, but there is a large cytosolic pool in controls absent in Alzheimer’s disease." (PMID 35611312, 2022).
atrial fibrillation (1 paper, 2017). A disorder characterized by an electrocardiographic finding of a supraventricular arrhythmia characterized by the replacement of consistent P waves by rapid oscillations or fibrillatory waves that vary in size, shape and timing and are accompanied by an irregular ventricular response. "Possibly, dysregulation of PDE1A activity could contribute to the increased prevalence of atrial fibrillation reported in ADPKD." (PMID 28750036, 2017).
autism spectrum disorder (1 paper, 2023). A spectrum of developmental disorders that includes autism, and Asperger syndrome. "We also observed PDEs (which hydrolyzes both cAMP and cGMP) was associated with psychiatric disorders [OR of PDE1A was 1.0836 for autism spectrum disorder; OR of PDE2A was 0.8968 for Tourette syndrome (TS) and 0.9449 for SCZ; and OR of PDE3A was 0.9796 for MDD; P < 0.05]." (PMID 37605207, 2023).
breast carcinoma (1 paper, 2025). "This set comprised senescence markers (CDKN1A, LMNB1, MKI67), apoptosis regulators (BCL2, BCL2L1), a highly overexpressed gene (ITGB6), and drug targets (ACTA2, GSDMC, KRT6A, PDE1A, PSMA8), all of which showed strong concordance with our RNA-seq data in all four breast cancer cell lines." (PMID 40312750, 2025).
cardiac failure (1 paper, 2024). "In the heart, PDE1A acts through regulation of cGMP levels, and PDE1 inhibition improved proteasomal degradation of a misfolded protein in a mouse model of proteinopathy-induced cardiac failure, but we do not yet know whether this may be similarly useful in HD models." (PMID 39428482, 2024).
depression (1 paper, 2011). "Although our findings indicating associations of SNPs in PDE1A, PDE9A, and PDE11A with MDD and antidepressant treatment response failed to reproduce in an independent sample of MDD patients versus controls (the sequenced treatment alternatives to relieve depression/STAR*D sample)." (PMID 22654729, 2011).
dysautonomia (1 paper, 2023). An acute or chronic disorder, affecting the sympathetic or parasympathetic nervous system. "The identified genes, including SEMA3D and PDE1A, may serve as potential diagnostic biomarkers for differentiating between CD and UC, as well as therapeutic targets for restoring enteric dysautonomia and SMC proliferative disorders in CD." (PMID 37727374, 2023).
glioblastoma (1 paper, 2022). The most malignant astrocytic tumor (WHO grade IV). "Expression of A-kinase anchoring protein 1(AKAP1), which attaches PKA to the cytoskeleton, as well as phosphodiesterase 1A (PDE1A), a cAMP-degrading enzyme, were shown to be increased in glioblastoma specimens, whereas the catalytic subunit of PKA was found to be decreased in high-grade gliomas." (PMID 35805104, 2022).
Hydrocephalus (1 paper, 2017). Hydrocephalus is an active distension of the ventricular system of the brain resulting from inadequate passage of CSF from its point of production within the cerebral ventricles to its point of absorption into the systemic circulation. "Interestingly, depletion of either, PDE1A or PDE3A using morpholinos causes pronephric cysts, body curvature, and hydrocephalus in zebrafish." (PMID 28750036, 2017).
lung carcinoma (1 paper, 2025). "Additionally, the overexpression of PDE1A was also observed in lung cancer from high-risk patients compared with low-risk patients (p<0.0001)." (PMID 40704992, 2025). "(C and D) Box plot analysis of the PDE1A messenger RNA (mRNA) levels in clinical lung cancer tissue samples." (PMID 40704992, 2025). "In addition, it is worth testing if PDE1A inhibition affects metastasis in lung cancer models and sensitizes cisplatin in resistant NSCLC cells in vitro and in vivo." (PMID 40704992, 2025). "High expression of phosphodiesterase 1A (PDE1A) predicts a poor prognosis of lung cancer patients." (PMID 40704992, 2025). "GSEA demonstrated that PDE1A expression was positively correlated with angiogenesis in lung cancer." (PMID 40704992, 2025). "Thus, PDE1A might be a novel prognostic predictor in lung cancer treatment and contribute to lung cancer progression." (PMID 40704992, 2025). "Single-user input genes: PDE1A; Cancer type: LUNG; Survival measure: death; Bifurcate gene expression at: median; GSE30219-Off-context gene expression in lung cancer identifies a group of metastatic-prone tumors." (PMID 40704992, 2025).
melanoma (1 paper, 2023). A malignant, usually aggressive tumor composed of atypical, neoplastic melanocytes. "The target of curcumin is phosphodiesterase 1A (PDE1A), which plays an important role in the proliferation of melanoma cells." (PMID 37630248, 2023). "Interestingly, the overexpression of PDE1A up-regulates the expression of UHRF1 and DNMT1, and also inhibits the antiproliferative effect of curcumin in B16F10 (murine melanoma) cells." (PMID 37630248, 2023).
myxoma (1 paper, 2024). A benign soft tissue neoplasm characterized by the presence of spindle and stellate cells, lobulated growth pattern, and myxoid stroma formation. "One of the most notable findings was significant upregulation of cyclic nucleotide phosphodiesterase (PDE) gene families, including PDE3A, PDE1A, PDE7B, and PDE10A in myxoma cells." (PMID 39090109, 2024).
synucleinopathies (1 paper, 2017). "In conclusion, this work identifies inhibition of PDE1A in particular as promising target for neuroprotective treatment of synucleinopathies." (PMID 28904388, 2017). "In conclusion, this work identifies that inhibition of PDE1A and/or PDE1C might be useful in the prevention or treatment of synucleinopathies." (PMID 28904388, 2017).
testicular cancer (1 paper, 2023). A primary or metastatic malignant neoplasm that affects the testis. "Another gene that was found to be significantly associated with testicular cancer was PDE1A and in vivo exposure of mice to secondhand smoke produced a unique ‘frameshift’ variant within the murine PDE1A suggesting an involvement of this PDE in non-familial testicular cancer." (PMID 37108780, 2023).
vascular hypertrophy (1 paper, 2016). "Moreover, a single nucleotide polymorphism in PDE1A was associated with elevated diastolic blood pressure and vascular hypertrophy suggesting a role of the PDE1A isoform in human vascular function [27•]." (PMID 27079836, 2016).
tumor (5 papers, 2013 to 2026). "The role of YTHDF2 in PDE1A-driven tumor metastasis should be elucidated in future studies." (PMID 40704992, 2025).
cancer (4 papers, 2019 to 2025). A tumor composed of atypical neoplastic, often pleomorphic cells that invade other tissues. "Notably, PDE1a has also been shown to regulate cell motility and the migration of cancer cells via cGMP/PKG." (PMID 37887031, 2023). "Phosphodiesterase 1 (PDE1s: PDE1A; PDE1B; PDE1C) targets second messengers (cAMP and cGMP) to regulate diverse physiological processes, with limited exploration in cancer." (PMID 38962317, 2024). "PDE1A might be involved in the adhesion, migration, and motility of NSCLC cells, which are critical parameters in the metastatic dissemination of cancer cells." (PMID 40704992, 2025). "DAG and IP3 signaling was not enriched with cancer drivers and did not have any low affinity CT drug targets, but did have six high affinity NP targets: PRKCG, E,A,D (Protein Kinase C), PDE1A (Phosphodiesterase 1A) and ADCY1 (Adenylate Cyclase 1)." (PMID 31214023, 2019).
kidney diseases (1 paper, 2023). "Strong PDE1A expression was seen in the kidney, suggesting their possible involvement in kidney diseases.We found that PDE1A was a key gene of DKD, which is related to focal adhesion and lysine degradation pathways." (PMID 37063851, 2023).
PDE1A also shares sentences with these, for which no sentence is quoted: polycystic kidney disease (2 papers); Crohn disease (1); eczema (1); Fraser’s syndrome 1 (1); glioma (1); idiopathic pulmonary arterial hypertension (1); liver fibrosis (1); metastatic melanoma (1); multiple sclerosis (1); myocardial infarction (1); nephrogenic diabetes insipidus (1); nephrolithiasis (1); ovarian carcinoma (1); proteinopathy (1); psychiatric disorder (1); pulmonary disorders (1); pulmonary hypertension (1); Renal cyst (1); spinal cord injury (1); teratospermia (1); Tourette syndrome (1).